TAF15 (TATA-box binding protein associated factor 15)
Diseases named in the same sentence as TAF15 in open-access papers (continued):
Sharing a sentence is not in itself a finding about the gene and the disease.
lung squamous cell carcinoma (10 papers, 2020 to 2025). "Recently, LINC00649 has been revealed to interact with TAF15 to facilitate the progression of lung squamous cell carcinoma by enhancing MAPK6 expression and activating the MAPK signaling pathway." (PMID 36895010, 2023). "Recently, it has been reported that TAF15 affects MAPK6 expression by stabilizing MAPK6 mRNA in lung squamous cell carcinoma (LUSC) cells." (PMID 36895010, 2023). "Similar observations were made in lung squamous cell carcinoma, in which TAF15 was found to promote cell proliferation, migration and invasion by activating the MAPK signaling pathway." (PMID 37037864, 2023). "PITPNA-AS1 recruited TAF15 to maintain HMGB3 in lung squamous cell carcinoma cells." (PMID 34496348, 2021). "On the other hand, RNA binding protein TAF15, acting as an RNA stabilizer, is reported to be recruited by lncRNA PITPNA‐AS1 to stabilize HMGB3 mRNA, enhancing proliferation and migration of lung squamous cell carcinoma cells." (PMID 39715205, 2024). "TAF15 has been reported function as an RBP that interacts with several lncRNAs in various diseases, such as breast cancer, lung squamous cell carcinoma, and hepatic ischemia–reperfusion injury." (PMID 38057891, 2023). "LINC00649 was revealed to recruit TAF15, an element stabilizing the expression of mitogen-activated protein kinase 6 (MAPK6), thus activating the MAPK signaling pathway in lung squamous cell carcinoma." (PMID 37504305, 2023). "In lung squamous cell carcinoma, PITPNA-AS1 was also observed to boost tumor cells' proliferating and migrating processes via recruiting TAF15 for stabilizing HMGB3 mRNA." (PMID 34055841, 2021). "For instance, a study unveiled the involvement of LINC00649 in recruiting TAF15 to stabilize MAPK6 expression, thereby promoting the progression of lung squamous cell carcinoma through activation of the mitogen-activated protein kinase (MAPK) signaling pathway." (PMID 39735666, 2025). "Moreover, lncRNA PITPNA-AS1 recruits TAF15 to stabilize HMGB3 mRNA to promote the proliferation and migration of lung squamous cell carcinoma cells." (PMID 36895010, 2023).
leukemia (7 papers, 2008 to 2025). A malignant (clonal) hematologic disorder, involving hematopoietic stem cells and characterized by the presence of primitive or atypical myeloid or lymphoid cells in the bone marrow and the blood. "Furthermore, additional genes can also exacerbate non-neurodegenerative disease phenotypes, such as glaucoma (optineurin, OPTN), Enterovirus-induced Type-1 diabetes (Peripherin, PRPH), leukemia, or cancer (TATA-box-binding protein-associated factor 15, TAF15)." (PMID 37566027, 2023).
acute leukemia (6 papers, 2014 to 2021). A clonal (malignant) hematopoietic disorder with an acute onset, affecting the bone marrow and the peripheral blood. "Oncogenic alterations of TAF15 have been previously characterized in cases of acute leukemia, wherein gene translocations give rise to fusion protein of TAF15 N-terminal domain with other transcription factors such as CIZ/NMP412." (PMID 26612539, 2015).
glioma (6 papers, 2021 to 2023). A benign or malignant brain and spinal cord tumor that arises from glial cells (astrocytes, oligodendrocytes, ependymal cells). "Taken together, the TAF15/LINC00665/MTF1(YY2)/GTSE1 axis has been acknowledged as an important axis in the modulation of the malignant features of glioma cells." (PMID 36429005, 2022). "The PABPC1-BDNF-AS-RAX2-DLG5 axis was shown to play the same role as the TAF15/LINC00665/MTF1(YY2)/GTSE1 axis in regulating the biological behavior of gliomas." (PMID 34178684, 2021). "To verify our hypothesis, we immunoprecipitated endogenous NOP58 and performed immunoblotting with a TAF15 antibody in glioma cells." (PMID 37980347, 2023). "In glioma cells, in vitro experiments have indicated down-regulation of TAF15 and LINC00665." (PMID 36429005, 2022). "In glioma, the TAF15|LINC00665/MTF1|YY2/GTSE1 axis inhibits malignant tumor progression.TATA-box-binding protein-associated factor 15 (TAF15) is a member of the FET family and plays an important role in regulating mRNA transcription, RNA splicing, and trafficking." (PMID 35563845, 2022). "However, another view is that LINC00665 can act as a protective factor for glioma, inhibiting the malignant development of the tumor through the TAF15|LINC00665/MTF1|YY2/GTSE1 axis." (PMID 35563845, 2022). "Notably, the ability to stabilize mRNA is not necessarily oncogenic, in fact recently it was found that TAF15 was downregulated in glioma cells." (PMID 33469081, 2021). "Such key role of TAF15 the behaviour of glioma cells, appears in line with our results." (PMID 33469081, 2021). "To explore the effect of INHEG on the association between TAF15 and NOP58, we performed endogenous co-immunoprecipitation of TAF15 and NOP58 in INHEG transcriptionally activated glioma cells." (PMID 37980347, 2023). "Immunoprecipitation of endogenous NOP58 followed by immunoblotting with SUMO2 antibody in TAF15-knockdown cells and control cells indicated that endogenous NOP58 sumoylation was reduced after treating glioma cells with TAF15-targeted siRNAs." (PMID 37980347, 2023). "Overexpressed TAF15 stabilized long intergenic non-protein coding RNA 665, inhibiting the malignancy of glioma cells." (PMID 33469081, 2021). "Additionally, overexpression of TAF15 stabilizes LINC00665, leading to reduced STAU1-mediated mRNA degradation of both MTF1 and YY2, thereby restricting GTSE1 transcription and ultimately disrupting glioma’s malignant progression." (PMID 37403043, 2023). "Additionally, the TAF15/LINC00665/MTF1(YY2)/GTSE1 axis is crucial for regulating the malignant biological behaviors of glioma cells, which might help in the development of a novel therapeutic strategy for human glioma." (PMID 34178684, 2021).
proteinopathy (5 papers, 2022 to 2026). "Our findings demonstrated that GstO2 was a pathogenic regulator of TAF15-associated proteinopathies." (PMID 36411469, 2022). "In the present study, we aimed to examine the neuroprotective role of GSTO in the Drosophila model of TAF15-associated proteinopathies." (PMID 36411469, 2022). "The structures of TAF15 filaments will guide the development of model systems to enable studies of disease mechanisms, and will provide a basis for the design of diagnostic and therapeutic tools targeting TAF15 proteinopathy in neurodegenerative disease." (PMID 38057661, 2024). "The structure of TAF15 amyloid filaments provides a basis for the development of model systems of neurodegenerative disease, as well as for the design of diagnostic and therapeutic tools targeting TAF15 proteinopathy." (PMID 38057661, 2024). "Therefore, the regulation of TAF15 stability in the cytoplasm is a critical therapeutic mechanism for TAF15-associated proteinopathies." (PMID 36411469, 2022). "Therefore, GstO2 may play a protective role in the neuronal cells of Drosophila by suppressing the excessive ROS production from mitochondria in TAF15-associated proteinopathies." (PMID 36411469, 2022). "The formation of TAF15 amyloid filaments with a characteristic fold in FTLD establishes TAF15 proteinopathy in neurodegenerative disease." (PMID 38057661, 2024).
lung adenocarcinoma (4 papers, 2013 to 2025). A carcinoma that arises from the lung and is characterized by the presence of malignant glandular epithelial cells. "This study aimed to investigate the effects of the interaction between ROP16 and TAF15 on apoptosis and cell cycle regulation in A549 lung adenocarcinoma cells." (PMID 40684184, 2025). "In this study, we pay more attention to the effect of TAF15 silencing on the functions of different genotypes of ROP16 to clarify part of the mechanism by which ROP16 inhibits the malignant biological behavior of lung adenocarcinoma cells." (PMID 40684184, 2025). "Inhibition of the malignant progression of lung adenocarcinoma is achieved by TIFI-γ, which can regulate IL-6 transactivation by disrupting TAF15/tbp." (PMID 37573347, 2023). "Some of the genes such as PIK3CA, TAF15, VAPB, Appl1, Rab5a, ARF4, and XIAP in Merged-module activate the PI3K-Akt pathway and are overexpressed in a manner similar to that of EGFR in lung adenocarcinoma." (PMID 23874428, 2013).
lung carcinoma (4 papers, 2020 to 2026). "Previous studies showed TAF15 knockdown significantly inhibits the proliferation of melanoma and lung cancer cells." (PMID 37037864, 2023). "To identify the role TAF15 plays in lung cancer cells, we performed co-immunoprecipitation of TAF15 from A549 and H460 lysates." (PMID 32676166, 2020). "Immunohistochemistry analysis of lung cancer TMA revealed a higher expression of TAF15 when compared to matched healthy lung tissue." (PMID 32676166, 2020). "We found approximately a 3-fold increase in the percentage of TAF15 positive cells in A549 (at 48–72 h) and H460 (72 h) lung cancer cells following 3Gy irradiation." (PMID 32676166, 2020). "Thus, TAF15 protein is overexpressed in lung cancer, and this elevated expression level correlates with cancer death." (PMID 32676166, 2020). "We found high expression of TAF15 in NSCLC (black arrows) and that expression levels correlated with increasing stage and grade of lung cancer." (PMID 32676166, 2020).
breast carcinoma (3 papers, 2023 to 2024). "For instance, Linc00504 recruited TAF15 to stabilize CPEB2 mRNA, thereby affecting the radio-sensitivity of breast cancer." (PMID 38057891, 2023).
colorectal cancer (3 papers, 2023 to 2024). A primary or metastatic malignant neoplasm that affects the colon or rectum. "In colorectal cancer, TRPM2-AS recruited TATA-box-binding protein-associated factor 15 (TAF15) to maintain the stability of its neighboring TRPM2 mRNA, thereby increasing its expression." (PMID 38532427, 2024). "Similarly, TAF15 interacts with TRPM2-AS to maintain the stability of TRPM2 mRNA, promoting cell proliferation in colorectal cancer." (PMID 39715205, 2024).
cutaneous squamous cell carcinoma (3 papers, 2019 to 2023). "The up-regulation of LINC01048 induced by USF1 promotes cell proliferation and apoptosis in cutaneous squamous cell carcinoma by binding to TAF15 to activate YAP1 transcription." (PMID 32776110, 2020). "For instance, LINC01048 increases the binding of TAF15 to YAP1 promoter and gives rise to sustaining activation of Hippo pathway and hence promotes cell proliferation in cutaneous squamous cell carcinoma." (PMID 37257820, 2023).
dementia (3 papers, 2019 to 2024). Loss of intellectual abilities interfering with an individual's social and occupational functions. "Importantly, abnormal aggregates of TAF15 in the brain have been linked to the early onset of dementia." (PMID 38874013, 2024). "FUS‐ and TAF15‐immunoreactive aggregates have been readily observed in the brains of individuals with early‐onset dementia." (PMID 38874013, 2024). "TAF15 may play an important role in spine pathology and memory deficits, as a recent study has identified abnormal aggregates of TAF15 in the brains of individuals with early‐onset dementia." (PMID 38874013, 2024).
squamous cell carcinoma (3 papers, 2020 to 2023). A carcinoma arising from squamous epithelial cells. "The expression level of LINC010148 can be elevated by USF1, and LINC010148 interacts with TAF15 to bind to the promoter of YAP1, which further triggers the development of squamous carcinoma." (PMID 34285657, 2021). "Similarly, MIR9-3HG can promote carcinogenesis of squamous cell carcinoma by affecting LIMK1 mRNA and protein levels via sponging miR-138-5p and recruiting TAF15, and it was also considered a predictive biomarker in HNSCC via multiple machine learning studies and q-RT PCR." (PMID 37312123, 2023).
chondrosarcoma (2 papers, 2019 to 2020). A malignant cartilaginous matrix-producing mesenchymal neoplasm arising from the bone and soft tissue. "The same holds true for rearrangements involving NR4A3 in extraskeletal myxoid chondrosarcomas: while the AMP-FPS assay covers the most NR4A3 common partners (EWSR1, TAF15, TCF12, TFG) it lacks probes for both NR4A3 and uncommon partners, thus scoring negative in the presence of alternative fusions." (PMID 32351889, 2020).
gastric cancer (2 papers, 2020 to 2023). A primary or metastatic malignant neoplasm involving the stomach. "In a prior study, a human IgM anti-TAF15 antibody, PAT-B4, isolated from a stomach cancer patient, targeted a variant of TAF15 expressed on the surface of cancer cells." (PMID 32676166, 2020). "A previous study showed that human antibody PAT-BA4 that recognizes a variant of cell surface TAF15 inhibits cancer cell motility and cell adhesion in stomach cancer and melanoma." (PMID 32676166, 2020). "However, the role and molecular mechanism of TAF15 in gastric cancer (GC) progression are still unknown." (PMID 37037864, 2023).
non-small cell lung carcinoma (2 papers, 2023). A group of at least three distinct histological types of lung cancer, including non-small cell squamous cell carcinoma, adenocarcinoma, and large cell carcinoma. "Moreover, studies have revealed that TAF15 is associated with the processes of various of malignant tumours including non-small cell lung cancer and melanoma." (PMID 37037864, 2023). "A potential target of TAF15 concerning resistance to radiotherapy, essential for non-small-cell lung cancer treatment, has been proposed." (PMID 37508851, 2023). "Overexpression of TAF15 is correlated with worsened survival in non-small cell lung cancer patients." (PMID 37037864, 2023).
acute lymphoblastic leukemia (1 paper, 2025). Leukemia with an acute onset, characterized by the presence of lymphoblasts in the bone marrow and the peripheral blood. "Critically, recurrent chromosomal translocations involving the ZNF384 gene, which result in fusion proteins with partners such as EWSR1, TAF15, and EP300, are frequently observed in the pathogenesis of acute lymphoblastic leukemia (ALL)." (PMID 41429980, 2025).
autism (1 paper, 2022). Persistent deficits in social interaction and communication and interaction as well as a markedly restricted repertoire of activity and interest as well as repetitive patterns of behavior. "Numerous RG/RGG-containing proteins have been implicated in neurological disorders, such as FUS and TAF-15 in ALS, FXR1, and FMRP1 in fragile X syndrome (FSX), SMN in spinal muscular atrophy (SMA), SHANK1 in autism, as well as a plethora of human cancers." (PMID 35203243, 2022).
breast adenocarcinoma (1 paper, 2025). "However, those not previously reported in the literature (colored by pink), including TAF15, HIST1H4I and FAM46C, may facilitate the identification of novel targets for the treatment of breast adenocarcinoma." (PMID 40768543, 2025).
essential tremor (1 paper, 2014). A relatively common disorder characterized by a fairly specific pattern of tremors which are most prominent in the upper extremities and neck, inducing titubations of the head. "We sequenced the exons coding the NES domains of five RNA-binding proteins (TARDBP, hnRNPA2B1, hnRNPA1, TAF15 and EWSR1) that have been previously implicated in neurodegeneration in a series of 257 essential tremor (ET) cases and 376 healthy controls." (PMID 25375143, 2014).
Huntington disease (1 paper, 2024). Huntington disease (HD) is a rare neurodegenerative disorder of the central nervous system characterized by unwanted choreatic movements, behavioral and psychiatric disturbances and dementia. "Both FUS and TAF15 were also detected in the detergent-insoluble fraction of the Huntington’s disease mice R6/2, indicating that TAF15 insolubility seems a secondary effect of FUS aggregation and is not due to exposure to injected FUS fibrils." (PMID 38862967, 2024).
Hypercholesterolemia (1 paper, 2013). An increased concentration of cholesterol in the blood. "Of the DEGs in the that were up-regulated in common between the hypertension only- and hypercholesterolemia plus sham groups (both vs. sham controls), Nibrin like (LOC100352398) showed the largest fold change, followed by TAF15, and ANKAR." (PMID 23874591, 2013).
Hypertension (1 paper, 2013). The presence of chronic increased pressure in the systemic arterial system. "Among the highly up-regulated genes in the MCA of the hypertension only group compared to sham controls were Nibrin like (LOC100352398), TAF15 and ANKAR." (PMID 23874591, 2013).
motor neuron disease (1 paper, 2024). "Our finding that TAF15 forms filaments in individuals with FTLD–FET, including those with upper and lower motor neuron pathology, should motivate genetic analysis of patient cohorts to elucidate the potential contribution of rare TAF15 mutations to FTLD and motor neuron disease." (PMID 38057661, 2024).
schizophrenia (1 paper, 2024). A major psychotic disorder characterized by abnormalities in the perception or expression of reality.
tauopathy (1 paper, 2018). Neurodegenerative disorders involving deposition of abnormal tau protein isoforms (tau proteins) in neurons and glial cells in the brain. "Interestingly, the third group of proteins whose association with tau increased in the 2.5 m mice was nucleotide binding proteins; these include RBPs such as EWSR1, TAF15 and HNRNPA0, which we previously reported to co-localize with tau pathology in the rTg4510 model of tauopathy." (PMID 30068389, 2018).